STAT3 (signal transducer and activator of transcription 3)
Diseases named in the same sentence as STAT3 in open-access papers (continued):
Sharing a sentence is not in itself a finding about the gene and the disease.
tumor (continued). "Clinically, tumors with high STAT3 activity display poorer responses to FOLFOX, increased recurrence rates, and a more immunosuppressive tumor microenvironment characterized by M2 macrophage polarization and reduced CD8+ T-cell infiltration." (PMID 41516350, 2026). "In the TCGA CCA cohort, high expression of IL6, TNF, AKT1, and STAT3 and low expression of PPARG correlated with advanced tumor stage and poorer overall survival (e.g., IL6: ρ = 0.42, p = 0.01)." (PMID 41899527, 2026). "SOCS3 overexpression or pharmacologic inhibition of JAK1/STAT3 markedly suppressed HIF-2α expression and tumor progression both in vitro and in vivo." (PMID 41874563, 2026). "Overall, these findings demonstrated that up-regulation of STAT3 and CD47 contributed to the evasion of tumour cells from macrophage-mediated phagocytosis." (PMID 41438583, 2026). "For instance, IL-6 blockade via monoclonal antibodies or JAK/STAT3 inhibitors has demonstrated early promise in solid tumors, including cervical cancer, by reducing proliferation, reversing EMT, and sensitizing tumor cells to chemotherapy and radiotherapy." (PMID 41497141, 2026). "Most STAT3 inhibitors work by preventing its dimerization through binding to the SH2 domain, blocking downstream signaling pathways involved in tumor progression and immune suppression." (PMID 41596231, 2026). "The free radical scavenging potential of Salvia coccinea and apigenin is responsible for reduced oxidative stress and tumor cell metastasis modulated through PARP-cleavage, caspase-3, ERK, CDK-1, JAK2/STAT3, Bax/Bcl-2, AMPK, and Wnt/β-catenin pathways." (PMID 41640995, 2026). "Low miR-133b levels correlate with increased phosphorylation of STAT3 (p-STAT3) and deregulation of the JAK2/STAT3/Bcl-2 axis, thereby promoting cell survival and tumor progression." (PMID 41596525, 2026). "TEFT inhibits GBM progression by suppressing the TGF‐β/SMAD2/3/STAT3/C1R axis, thereby attenuating EMT and reducing tumor aggressiveness." (PMID 41489302, 2026). "JUN, FOS, STAT3, JUND and NR2F1 were up-regulated in clusters C2 and C3, leading to tumor progression and immune evasion by influencing target genes HSPA1A, CXCL9 and PDGFR." (PMID 42074110, 2026). "Immunohistochemical analysis demonstrated 45.6% and 40.0% reductions in STAT3+ (P = 0.01) and STAT5+ (P = 0.0478) tumor cells, respectively." (PMID 41924268, 2026). "In tumor cells, signaling pathways such as PI3K/AKT/mTOR, JAK/STAT3, and TGF-β/Smad form a robust defense system." (PMID 41599293, 2026). "While STAT3/STAT5 are established oncogenes and STAT1/STAT2 are classically viewed as tumor suppressors, emerging evidence indicates context-dependent roles in tumorigenesis." (PMID 42195004, 2026). "Twist2 also affects critical signaling pathways like NF-κB and STAT3, which help create conditions in the TME that suppress the immune system and make it harder for the immune system to find and kill the tumor." (PMID 41596524, 2026). "Activation of STAT3 upregulates genes involved in cytokine production, angiogenesis, and EMT, thereby facilitating immune evasion and tumor invasion." (PMID 41497141, 2026). "HOTAIR (HOX transcript antisense RNA) contributes to MM pathogenesis through epigenetic repression of tumor suppressors and activation of NF-κB and JAK2/STAT3 signaling." (PMID 41596492, 2026). "Previous studies have indicated that increased phosphorylated STAT3 enhances Snail expression, triggers EMT, and promotes tumor progression." (PMID 41403696, 2025). "High levels of IL-6 in the TME promote tumor cell proliferation, survival, and invasiveness through the IL-6/JAK/STAT3 signaling pathway." (PMID 40430040, 2025). "This interaction augments the expression of STAT3 in RCC cells and mediates macrophage polarization, thereby facilitating tumor growth." (PMID 40490663, 2025). "CXCR7 is highly expressed in tumor endothelial cells and promotes HCC migration and invasion by influencing the phosphorylation of the STAT3 pathway." (PMID 40145607, 2025).
tumor (continued). "In vitro and in vivo models show that NiNPs activate the CDK1/STAT3/FASN axis to disrupt FAM homeostasis, conferring metabolic advantages for tumor cell proliferation and migration." (PMID 41226659, 2025). "For example, IL-6, a key NF-κB target, activates the STAT3 and MAPK pathways in tumor cells, promoting survival under hypoxic or nutrient-deprived conditions." (PMID 40562870, 2025). "Downregulation of STAT3 can decrease vascular endothelial growth factor (VEGF), crucial for tumor vitality and angiogenesis." (PMID 40118821, 2025). "For instance, in PDAC, leukemia inhibitory factor secreted by tumor cells and progranulin from macrophages activate myCAFs via the JAK/STAT3 pathway." (PMID 41164803, 2025). "IL6 activates STAT3 and MAPK, promoting chemotherapyresistance, tumor progression,and immune evasion.It contributes to immunesuppression andsupports metastasis." (PMID 40427188, 2025). "IL-6 can be produced by numerous stromal cells including CAFs, in addition to tumor cells themselves, and both paracrine and autocrine activation of the IL-6/JAK/STAT3 pathway in tumors has been reported." (PMID 40597443, 2025). "In glioblastoma, LDHA activates the ERK-YAP1/STAT3 axis, upregulating CCL2 and CCL7 to recruit macrophages, which in turn deliver LDHA to tumor cells via extracellular vesicles, forming a tumor-macrophage symbiotic loop that drives progression." (PMID 40734168, 2025). "Other studies showed that STAT3 inhibition enhanced STING signaling induced by STING agonists and synergistically increased the anti-tumor immunity response in animal models of TNBC." (PMID 40743845, 2025). "In combination with erlotinib, an EGFR tyrosine kinase inhibitor, fedratinib decreased STAT3 activation and increased apoptosis in erlotinib-resistant NSCLC cells, also inhibiting tumour growth in murine models." (PMID 40407951, 2025). "WP1066, a selective STAT3 inhibitor, can inhibit MDA-MB-231 tumor growth and brain metastasis in a mouse BC model." (PMID 40175348, 2025). "CAFs can secrete various soluble cytokines and growth factors, including IL-6, TGF - β, and CXCL12, which bind to receptors on tumor cells and activate oncogenic signaling pathways such as JAK/STAT3, PI3K/AKT, and MAPK." (PMID 40959080, 2025). "Intriguingly, tumor-derived exosomal miR-183-5p activates both HIF-1α and STAT3, establishing a link between hypoxic signaling and enhanced proteolysis." (PMID 40704145, 2025). "This study demonstrated that hypoxia induced tumor derived exosomal miR-1246 mediated M2 macrophage polarization by directly targeting TERF2IP to regulate the NF-κB and STAT3 signaling pathways, which promote the proliferation and metastasis of gliomas." (PMID 39928285, 2025). "In our study, we observed a significant reduction in tumor proliferation and an increase in apoptosis after treatment with the NLP-EXOSOME COMPLEX STAT3 silencer both in vitro and in vivo." (PMID 40427146, 2025). "STAT3 and ERK signaling: CPA4 is known to promote tumor progression through activation of the STAT3 and ERK signaling pathways in various cancers." (PMID 40805261, 2025). "Mechanistically, RBP4 can activate macrophages via exosomal signaling, trigger STRA6-mediated Janus kinase (JAK)/STAT3/STAT5 activation, and promote pro-inflammatory responses that support tumor progression, migration, and metastasis." (PMID 41007818, 2025). "For example, the simultaneous administration of palbociclib with a dual inhibitor of STAT3 and CDK2, named nifuroxazide, induced senescence in MDA-MB-231 TNBC cells and reduced tumour growth in TNBC xenograft models." (PMID 41388212, 2025).
tumor (continued). "In human melanoma (A375) cells, apigenin down-regulates STAT3 target genes matrix metalloproteinase 2 (MMP-2) and MMP-9, thereby suppressing tumor growth and invasion." (PMID 40490812, 2025). "Our finding that LSD1 promotes the STAT3 network and modulates the infiltration of CD8+ T cells in the tumor microenvironment also correlates with the overall survival of patients with OSCC from TCGA data." (PMID 40246812, 2025). "In tumor cells, continuous stimulation of the JAK2/STAT3 signaling pathway promotes MYC expression and enhances the effects of MYC on cell proliferation and metabolism, promoting the proliferation, survival, and invasion of tumor cells." (PMID 40944417, 2025). "These in vitro studies suggest that pterostilbene facilitates significant anti-tumor activity via anti-proliferative and pro-apoptotic mechanisms, possibly via downregulation of JAK/STAT3 pathway." (PMID 40227411, 2025). "Targeting STAT3 has emerged as a promising therapeutic strategy for the reversal of EMT and suppression of tumor aggressiveness in OS." (PMID 40941019, 2025). "Decreased Wip1 expression in EOC correlated with tumor metastasis and Platinum resistance mediated by a VEGF/STAT3-dependent mechanism ​." (PMID 40813689, 2025). "STAT-3 activity leads to an increase in vascular endothelial growth factor (VEGF) levels and plays a role in tumor angiogenesis." (PMID 40943781, 2025). "It was found that HIF1α, STAT3, and MYC were highly expressed in tumor tissues and were positively correlated with Linc01559 expression (Figure A2a)." (PMID 40722682, 2025). "At pH 6.5, several tumor models demonstrated aberrant IFN-γ induction of immunoproteasome subunits β1i and β2i, accompanied by diminished STAT1 activation and perturbed STAT3 signaling." (PMID 41293269, 2025). "According to research, brusatol and bruceine D activate the JNK /p38 MAPK signaling pathways while suppressing the activation of Stat3/NF-κB, PI3K/Akt/mTOR, and PI3K/Akt/NF-κB pathways, thereby inducing apoptosis in various tumor cells." (PMID 41156537, 2025). "In this study, we first discovered that IDET inhibits STAT3 phosphorylation in TNBC cells, thereby exerting its anti‐tumor activity." (PMID 40918170, 2025). "Sustained activation of pathways such as Janus kinase 2/signal transducer and activator of transcription 3 (JAK2/STAT3) and Toll-like receptor 4 (TLR4) promotes tumor proliferation, invasion, and metastasis." (PMID 41573719, 2025). "In promoting tumor proliferation and metastasis, B7-H3 primarily exerts anti-apoptotic effects via pathways such as Jak2/Stat3, PI3K/AKT, and E7/Rb, thereby enhancing tumor survival." (PMID 41463642, 2025). "STAT3, a member of the STAT family, plays a role in cell growth, apoptosis, tumor progression, and differentiation." (PMID 39780275, 2025). "Tumor-derived factors such as VEGF, IL-6, and IL-10 accumulate MDSCs which in turn secrete more VEGF via STAT3 signaling, thus augments angiogenesis." (PMID 40165901, 2025). "Chronic inflammatory signaling (e.g., IL-6/STAT3) and PI3K/AKT/mTOR activation contribute to an immune-excluded, myeloid-dominant tumor microenvironment (TME) and primary resistance to PD-1." (PMID 41374963, 2025). "Through the modulation of core signaling axes—including NF-κB, PI3K/Akt, and STAT3—KOR orchestrates diverse biological processes ranging from inflammation resolution and tissue repair to tumor suppression." (PMID 41573725, 2025). "STAT3, the core member of the STAT protein family, plays multifaced roles in the inflammatory responses and tumor progression." (PMID 40165901, 2025). "IL-6 is an important tumor-initiating factor in CRC, and the proliferative and survival effects of IL-6 are primarily mediated by the downstream transcription factor STAT3 36, which is the forward feedback loop of STAT3 that promotes cancer malignancy." (PMID 41281755, 2025).
tumor (continued). "STAT3 is an essential member of the STAT family, and abnormal STAT3 activity not only promotes tumor cell growth but also induces the expansion of tumor-supporting fibroblasts and inhibits antitumor immune responses." (PMID 40158127, 2025). "The STAT3/STAT5 signaling pathways promote the migration and invasion of tumor cells by enhancing epithelial–mesenchymal transition in LUAD." (PMID 40860289, 2025). "The study demonstrated that the cytokines VEGF and TNFα found in the tumor microenvironment enhance the interaction between YAP/TAZ and the transcription factor STAT3." (PMID 39936032, 2025). "Then, we compared the expression between JAK2 and NCAPD3 or STAT3 in GTEx normal tissues and TCGA tumor tissues, and found both NCAPD3 and STAT3 showed strong positive correlations with JAK2 in tumor tissues." (PMID 39917394, 2025). "Phenolic and flavonoid compounds exhibit anticancer activity via regulating signaling pathways, including STAT3, NF-κB, and CXCR4, while also influencing the tumor environment to improve the immune system." (PMID 40430962, 2025). "Conversely, in metastatic T24T cells, the knockdown of STAT3 mimics the action of miR-145 by upregulating FOXO1, which significantly represses anchorage-independent growth (tumor-forming ability)." (PMID 40689207, 2025). "Specifically, activation of the STAT3 pathway within NK cells enhances TGF-β secretion, which in turn induces EMT and a metastatic phenotype in tumor cells." (PMID 40430484, 2025). "Tumor size, weight, and volume were significantly reduced in the combination treatment group, with marked downregulation of phosphorylated AKT and STAT3 levels." (PMID 40242448, 2025). "By integrating these findings, Sun, Zhang, and colleagues identified a key mechanistic pathway in which elevated tumor glycolysis recruits monocytes and macrophages through the ENSA-K63la/SRC-pS12/STAT3-pY705/CCL2 axis." (PMID 40166931, 2025). "IL-6 acts as a potent growth factor for EC tumor cells, activating the JAK/STAT3 pathway, which promotes proliferation, survival, and invasion." (PMID 40746533, 2025). "The isolated tumor cells showed a constitutive hyperphosphorylation of the truncated STAT1 mutant, as well as STAT3, even before cytokine stimulation." (PMID 40287766, 2025). "Macrophages in the TME uptake lactate derived from the tumor, which further promotes the ENSA-K63la/SRC-pS12/STAT3-pY705 axis and increases CCL2 expression, enhancing the chemotactic effect on monocytes/macrophages." (PMID 39883522, 2025). "Under physiological conditions, STAT3 activation is transient; however, in CCA, it is constitutively activated, driving tumor progression through sustained transcription of oncogenic and survival-related genes." (PMID 41155242, 2025). "This combined treatment reduced tumor occurrence, volume, and weight while modulating critical pathways, including TGF-β, PI3K, IL-6, and JAK/STAT3." (PMID 39861761, 2025). "In HCC, STAT3 is a key oncogenic driver, with its phosphorylated form detected in approximately 60% of HCC cases, closely correlating with tumor aggressiveness." (PMID 40699663, 2025). "Ultimately, dihydroartemisinin prevents tumor immune escape by inhibiting the TGF-β, PI3K/Akt, and STAT3 signaling pathways to promote tumor eradication." (PMID 41347152, 2025). "Beyond its role in fibroblast activation, LCN2 regulates several oncogenic signaling pathways—including PI3K/AKT, STAT3, ERK/MAPK, NF-κB, and Wnt/β-catenin—that collectively promote tumor proliferation, immune evasion, and extracellular matrix remodeling." (PMID 40472740, 2025). "For small-molecule-based PROTACs targeting TFs, a prominent example is SD-36, a PROTAC designed to degrade signal transducer and activator of transcription 3 (STAT3), a key factor in tumor progression." (PMID 40507351, 2025). "Collectively, our results demonstrated profound anti-tumor activity of co-targeting BCLXL and STAT3, extending beyond HER2-amplified GC cells." (PMID 40075071, 2025).
tumor (continued). "Exosomes from OC patients’ ascites also contain higher concentrations of STAT3 and FAS, proteins that contribute to carcinogenesis and tumour dissemination." (PMID 40143147, 2025). "Dysregulation of the JAK/STAT3 signaling pathway is a well-established driver of CRC pathogenesis, promoting tumor progression and metastasis through enhanced proliferation, anti-apoptotic effects, and increased invasiveness." (PMID 41585878, 2025). "N4 effectively inhibits STAT3 dimerization, as well as crosstalk with EGFR and NF-κB, and animal models have shown that N4 was well tolerated and effectively suppressed tumor growth and metastasis." (PMID 40075607, 2025). "Mechanistically, STAT3 deletion lowers the levels of cell cycle mediators (c-MYC, cyclin D1, and cyclin E) and survival proteins (Bcl-xL) in tumor cells." (PMID 40399946, 2025). "HUVECs were pretreated with NF-κB signaling pathway inhibitors R7050 (10 μM) and BAY 11-7082 (10 μM), as well as the STAT3 inhibitor Stattic (10 μM), for 1 h before the addition of NPC tumor cell supernatants." (PMID 40000620, 2025). "Analysis of basal protein levels revealed that total expression of STAT1, STAT2, and STAT3 remained largely unaffected in both STAT2 KO and IFNAR1 KO tumor cells, indicating that deletion of either gene does not alter steady-state STAT2 protein abundance." (PMID 41440237, 2025). "Mechanistically, GH action activates several oncogenic signaling cascades in NSCLC, including the JAK2/STAT5/STAT3, PI3K/AKT, and MAPK/ERK pathways, which enhance tumor cell survival, proliferation, and drug resistance in many cancers." (PMID 41515995, 2025). "Whereas IL-6/STAT3 promotes the Bcl-XL, Mcl-1, and VEGF, to inhibit apoptosis and promote cell survival by increasing angiogenesis and blood supply to the tumor." (PMID 40843259, 2025). "Pollutants regulate tumor cell HSC interactions by activating key molecular signaling pathways, including NF-κB, STAT3, TGF-β/Smad, and Hedgehog signaling." (PMID 40137490, 2025). "IL-6 exerts its effects through the activation of several oncogenic pathways, including JAK/STAT3, PI3K/Akt, and MAPK, which promote tumor cell proliferation, inhibit apoptosis, and enhance metastatic potential." (PMID 41007818, 2025). "Given that increased activity of STAT3, NF-κB, EZH2, and HDAC3 has also been reported in other tumors, it will be interesting to investigate the role of IκBζ in additional tumor entities." (PMID 40562773, 2025). "STAT3 expression is significantly elevated in GBM tissues compared to normal brain cells, and its abnormal activation contributes to an immunosuppressive tumor microenvironment in GBM." (PMID 39975150, 2025). "CircHIPK3 has also been shown to sponge miR-124, a well-known brain-specific tumor suppressor miRNA, which promotes the migration and proliferation of glioma cells by derepressing its downstream targets, including CDK6 and STAT3." (PMID 40896358, 2025). "Conversely, some genes, including CXCR4, KITLG, STAT3, and TNFSF10, were downregulated, suggesting a potential suppression of specific pathways related to tumor proliferation and vascular development." (PMID 39861616, 2025). "By promoting CAF activation, ECM remodeling, and STAT3-mediated signaling, LCN2 establishes a crucial link between EGFRvIII-expressing tumor cells and stromal reprogramming, ultimately enhancing tumor growth and invasion." (PMID 40472740, 2025). "Of these, age (≥55 years), tumor size (≥4 cm), gross extrathyroidal extension (gross Ex, present), maximum LNM size (≥30 mm), and n-STAT3 score (<70) showed significant differences in the multivariate analysis." (PMID 41104968, 2025). "The STAT3 and TNFR–NF-κB signaling pathways further influence these processes, enhancing M1 and M2 macrophage production and tumor progression." (PMID 40636453, 2025).